GPHN (gephyrin)
Diseases named in the same sentence as GPHN in open-access papers (continued):
Sharing a sentence is not in itself a finding about the gene and the disease.
psychiatric disorder (3 papers, 2014 to 2024). A disorder characterized by behavioral and/or psychological abnormalities, often accompanied by physical symptoms. "Given that both Nlgn2 and the MDGA1 have been correlated with many psychiatric disorders, our data support the notion that cytosolic gephyrin aggregation may represent an interesting target for novel therapeutic strategies." (PMID 39284869, 2024). "As for the psychiatric disease variants we identified as targets of Δphotoperiod-driven selection, the two for MDD show different patterns: the risk allele frequency increases with Δphotoperiod for GPHN and decreases for NDFIP2/SPRY2." (PMID 25358694, 2014). "A further detailed understanding of how Nlgn2 and MDGA1 differentially regulate gephyrin aggregation, and how these aggregates affect GABAergic synapse function, may therefore be relevant towards identifying pathophysiological mechanisms in Nlgn2- and MDGA1-related psychiatric disorders." (PMID 39284869, 2024).
tumour (3 papers, 2023 to 2025). "Mutations of ARID2, CUL3, TET1, FBXW7, EZR and GPHN were frequently accompanied by copy number loss consistent with their predicted/documented tumour suppressor roles." (PMID 38106039, 2023).
GPHN also shares sentences with these, for which no sentence is quoted: molybdenum cofactor deficiency (4 papers); autism spectrum disorder (2); cognitive deficits (2); infection (2); liver cancer (2); neuropathies (2); adult T-cell leukemia (1); Apnea (1); Arthritis (1); biotinidase deficiency (1); brain disorder (1); cerebellar ataxia (1); Encephalopathy (1); epileptic seizures (1); febrile seizures (1); hemangioblastoma (1); hereditary xanthinuria (1); lung carcinoma (1); lymphoma (1); memory impairment (1); microcephaly (1); mood disorder (1); nonketotic hyperglycinemia (1); Parkinson disease (1); primary biliary cholangitis (1); Rett syndrome (1); schizencephaly (1); systemic sclerosis (1).